CAPZA3 (capping actin protein of muscle Z-line subunit alpha 3)
Description:
F-actin-capping proteins bind in a Ca(2+)-independent manner to the fast growing ends of actin filaments (barbed end) thereby blocking the exchange of subunits at these ends. Unlike other capping proteins (such as gelsolin and severin), these proteins do not sever actin filaments. May play a role in the morphogenesis of spermatid (By similarity).
Synonyms: GSG3; CAPPA3; HEL-S-86
Tractability: No criterion of Open Targets' tractability assessment is met for any kind of drug.
Gene: Protein-coding gene on chromosome 12 (18,738,119 to 18,739,188, forward strand). Ensembl gene ENSG00000177938.
Subcellular location: Cytoplasm, cytoskeleton
Subcellular location (Human Protein Atlas): Calyx
Pathways (Reactome):
Vesicle-mediated transport: COPI-independent Golgi-to-ER retrograde traffic; COPI-mediated anterograde transport
Cellular responses to stimuli: HSP90 chaperone cycle for steroid hormone receptors (SHR) in the presence of ligand
Immune System: MHC class II antigen presentation
Gene Ontology:
Molecular function: actin filament binding
Biological process: barbed-end actin filament capping; actin filament organization
Cellular component: nucleus; cortical cytoskeleton; cytosol; F-actin capping protein complex; perinuclear theca; cytoplasm; cytoskeleton; membrane; sperm head
Genetic constraint (gnomAD): Loss-of-function variants: 22 observed, 23.99 expected, observed/expected ratio (o/e) 0.92, 90% interval 0.65 to 1.31. The upper end of that interval is the gene's LOEUF score, 1.31, which puts it in group 5 of 6, group 1 being the genes least tolerant of losing a copy. Missense variants: 353 observed, 357.06 expected, observed/expected ratio (o/e) 0.99, 90% interval 0.9 to 1.08. Synonymous variants: 141 observed, 133.41 expected, observed/expected ratio (o/e) 1.06, 90% interval 0.92 to 1.22.
Homologues: Orthologues: chimpanzee CAPZA3 (99% identical), macaque CAPZA3 (98% identical), rabbit CAPZA3 (93% identical), dog CAPZA3 (92% identical), mouse Capza3 (91% identical), rat Capza3 (90% identical), pig CAPZA3 (90% identical), guinea pig CAPZA3 (81% identical), Drosophila melanogaster cpa (31% identical), Caenorhabditis elegans cap-1 (27% identical). Paralogues in human: CAPZA1 (35% identical), CAPZA2 (34% identical).
Diseases named in the same sentence as CAPZA3 in open-access papers:
CAPZA3 is named in the same sentence as 3 diseases in open-access papers, as found by Europe PMC text mining. Sharing a sentence is not in itself a finding about the gene and the disease. The quoted sentences say what the papers report.
cryptorchidism (1 paper, 2023). The failure of one or both testes of a male fetus to descend from the abdomen into the scrotum during the late part of pregnancy. "According to the extent of difference between cryptorchidism and normal testis, the expression of seven downregulated genes (PLCZ1, AKAP4, AKAP3, IZUMO1, SPAG6, CAPZA3, and ROPN1L) were further selected for validation by qPCR." (PMID 38027210, 2023).
tumor (1 paper, 2020). "While CAPZA1, CAPZA2 and CAPZB, but not CAPZA3 levels correlated well with PIM1 levels in all tumor tissues, similar correlations were also observed for PIM2 and PIM3 in the samples with high Gleason scores." (PMID 32771000, 2020).
CAPZA3 also shares sentences with these, for which no sentence is quoted: infertile (2 papers).